EGFR (epidermal growth factor receptor)
Diseases named in the same sentence as EGFR in open-access papers (continued):
Sharing a sentence is not in itself a finding about the gene and the disease.
xerosis (21 papers, 2010 to 2026). "The physiopathology of xerosis associated with targeted therapies, especially EGFR inhibitors, seems to be related to the process of epidermal differentiation and homeostasis." (PMID 36990917, 2023). "As for xerosis, it affected 12 patients (6.0%) and was mostly caused by EGFR inhibitors (panitumumab, erlotinib and gefitinib)." (PMID 34844792, 2022). "One of the groups with the greatest association is the anti-EGFR, which can cause xerosis in up to 35% of the patients and, in this research, was responsible for two-thirds of the cases." (PMID 34844792, 2022). "The resulting inflammatory cell recruitment and subsequent cutaneous injury account for the majority of dermatological symptoms associated with anti-EGFR therapy including papulopustular eruption, hair growth disorders, periungual and nail plate abnormalities, xerosis, telangiectasias, and pruritus." (PMID 20680104, 2010). "Moreover, skin disorders such as dry skin caused by epidermal growth factor receptor inhibitor administration may also be associated with decreased skin expression of AQP3." (PMID 34205315, 2021). "Inhibition of EGFR signaling, which plays a critical role in epidermal homeostasis, results in various mucocutaneous toxicities, most notably xerosis, pruritus, and acneiform eruptions." (PMID 40868155, 2025). "Xerosis (dry skin) is among the most frequent dermatologic adverse effects of EGFR inhibitors and often presents with greasy scaling resembling seborrheic dermatitis." (PMID 40868155, 2025). "Articles have concluded that the incidence of xerosis was higher with some drug classes, among them EGFR inhibitors." (PMID 36990917, 2023). "The inhibition of EGFR in normal skin leads to alterations of growth and migration of keratinocytes that, together with inflammatory reactions, lead to xerosis and papulopustolar skin rash." (PMID 22640460, 2012). "EGFR-TKIs not only suppress the proliferative activity of basal keratinocytes but also facilitate their transition toward terminal differentiation, ultimately leading to xerosis of the skin." (PMID 41570298, 2026). "Additionally, the toxicity of other EGFR targeted therapies such as erlotinib and gefitinib is related to signal-triggering and tyrosine kinase inhibition resulting in xerosis, pruritus, alopecia, and hand and foot reactions, among others." (PMID 39330834, 2024). "Occurrence of xerosis instead was higher with hormonal therapy than with EGFR-inhibitors p < 0.005." (PMID 22640460, 2012). "In particular, epidermal growth factor receptor (EGFR) inhibitors and tyrosine kinase inhibitors (TKIs) have been reported to lower serum zinc levels, potentially contributing to dermatologic toxicities such as xerosis and pruritus." (PMID 41395599, 2025). "Furthermore, due to the dysfunction of EGFR, the release of cytokines such as IL-6 and TNF-α and the decreased production of cell adhesion factors such as claudin resulted in dry skin." (PMID 32252690, 2020). "Thus, we investigated whether the phosphorylation of EGFR and ERK was similarly suppressed in the skin of an erlotinib-induced dry skin mouse model." (PMID 32260143, 2020). "In particular, treatment with epidermal growth factor receptor (EGFR) inhibitors may result in the manifestation of dAEs, such as papulopustular rash, xerosis, and pruritus, in more than 80% of patients; this can lead to dose reduction or therapy discontinuation." (PMID 31049724, 2019).
adenocarcinoma in situ (20 papers, 2013 to 2025). A lesion in which the normally situated glands are partially or completely replaced by atypical cells with malignant characteristics. "Typically, EGFR mutations are more frequently detected in patients with early-stage disease with predominant lepidic lesions, such as adenocarcinoma in situ (AIS)." (PMID 39281386, 2024). "First, in our previous histopathological study, we showed that adenocarcinoma in situ, previously classified as bronchioloalveolar carcinoma, has significantly higher EGFR mutation frequency and DPYD mRNA levels than other histological types." (PMID 27268079, 2016). "At the opposite, 1 out of the EGFR mutated precursor lesions (in situ adenocarcinoma and atypical adenomatous hyperplasia), had an increased EGFR CN (CN: 3.4)." (PMID 24885034, 2014). "What's more, we found that the mutation of EGFR increased significantly from adenocarcinomas in situ (AIS, 21.4%) to microinvasive adenocarcinomas (MIA, 52.4%) and invasive adenocarcinomas (IA, 61.1%), while the mutation of ERBB2 dropped markedly from AIS (21.4%) to MIA (9.5%) and IA (4.1%)." (PMID 38496837, 2024). "EGFR mutations are significantly associated with the low-grade group (adenocarcinoma in situ [AIS]/minimally invasive adenocarcinoma [MIA]) and the intermediate-group (lepidic/acinar/papillary/invasive mucinous adenocarcinoma) rather than the high-grade group (solid/micropapillary)." (PMID 27861565, 2016). "Thus, it is unlikely that the adenocarcinoma in situ in the left lung has EGFR mutation." (PMID 23617234, 2013). "As the lesion progresses to adenocarcinoma in situ (AIS) and minimally invasive adenocarcinoma, mutations or overexpression in the epidermal growth factor receptor (EGFR) pathway also begin to show their significance." (PMID 39991629, 2025). "The pathological morphology of ground-glass pulmonary nodules often undergoes atypical adenomatous hyperplasia (AAH) → adenocarcinoma in situ (AIS) → minimally invasive adenocarcinoma (MIA) → invasive adenocarcinoma (IAC), even in patients with EGFR mutations." (PMID 39943992, 2024). "The genotypes were all EGFR L858R mutations, but the pathological type of P20T1 was lepidic predominant, and P20T2 was adenocarcinoma in situ." (PMID 34804960, 2021). "More than half of the patients with preinvasive adenocarcinoma in situ, minimally invasive, acinar, micropapillary and papillary subtypes were also EGFR‐mutants." (PMID 31692283, 2020). "Among the patients with preinvasive adenocarcinoma in situ (AIS) subtype, EGFR mutations were detected in 52% (16/31) of the patients." (PMID 31692283, 2020). "We attribute this difference to the inclusion in our cohort of a number of patients who had tumours of the adenocarcinoma in situ (AIS) subtype (29.7%), in which the frequency of EGFR mutations was reported to be 27.3% or 23.8%." (PMID 29849818, 2018). "The presently identified signal regulation supports our previous proposal that invasive adenocarcinoma and adenocarcinoma in situ might have different biological properties due to different EGFR signal cascade regulation and DPD activity." (PMID 27268079, 2016). "We searched for EGFR mutations for exons 18, 19, 20, and 21 in the genomic DNA from the adenocarcinoma in situ, but none of them were found (data not shown)." (PMID 23617234, 2013). "In contrast, adenocarcinoma in situ (AIS) and adenocarcinoma showed strong expression of RTKs (EGFR, HER2 or c-Met) on the cell membrane in 41 (77.4%) of the 53 cases." (PMID 28859123, 2017).
cervical squamous cell carcinoma (20 papers, 2005 to 2025). A squamous cell carcinoma arising from the cervical epithelium. "Studies have shown E6 protein expressed by high-risk HPV upregulated EGFR transcription in cervical squamous cell carcinoma by destabilizing the histone demethylase KDM5C on super-enhancers." (PMID 32850421, 2020). "Previous studies found a strong correlation between poor prognosis and EGFR gene amplification in patients with cervical squamous cell carcinoma." (PMID 33736612, 2021). "Previous studies have shown that EGFR and HER2 co-expression was implicated in an increase in tumor aggressiveness and worse prognosis of several cancers, including cervical squamous cell carcinoma." (PMID 28859123, 2017). "A significant association was observed between high EGFR levels and poor DFS in squamous cell cervical cancer patients (HR: 2.06, 95% CI: 1.43–3.01)." (PMID 27438047, 2016). "We have furthermore shown that CXC chemokine receptor 4 (CXCR4), CXCR7 and epidermal growth factor receptor (EGFR) were more frequently expressed in cervical squamous cell carcinoma than adenocarcinoma." (PMID 25795131, 2015). "In patients with squamous cell carcinoma of cervix, EGFR is overexpressed in up to 85% of cases, and EGFR expression has been associated with a later tumor stage and a poorer prognosis." (PMID 24860830, 2014). "The EGFR amplification significantly correlated with shorter overall survival (P=0.001) in cervical squamous cell carcinomas." (PMID 21730982, 2011). "In squamous cervical cancers in particular, proto-oncogenes, such as EGFR (7q12), MYC (8q24), ERBB2 (17q11.2-12), CCND1 (11q13), HRAS (11q15.5), and cIAP1 (11q22) are often activated by amplification." (PMID 21730982, 2011). "High-level EGFR expression (EGFR immunointensity of 2+ or 3+) was observed in 37% (22 out of 59) of the analysed cervical squamous cell carcinomas." (PMID 21730982, 2011). "The mechanism for EGFR overexpression in the majority of cervical squamous cell carcinomas remains to be identified." (PMID 21730982, 2011). "Cervical squamous cell carcinoma frequently exhibits EGFR overexpression, and the chemotherapeutic agents administered (nab-paclitaxel plus nedaplatin) likely suppressed tumor proliferation and factor secretion, thereby indirectly inhibiting cutaneous signaling activation." (PMID 41357602, 2025). "EGFR is known to be up-regulated in 40–50% of cervical squamous cell carcinomas." (PMID 35008200, 2021). "Our findings indicated that CD109 facilitates tumorigenicity and cancer aggressiveness, which might be mediated by EGFR/STAT3 signalling in cervical squamous cell carcinoma." (PMID 32507856, 2020). "Our data suggest that EGFR signalling is important in a subset of cervical squamous cell carcinomas and that anti-EGFR therapy may benefit patients who carry the 7p11.2 amplicon in their tumours." (PMID 21730982, 2011). "Interestingly, we found a strong correlation between poor prognosis and EGFR gene amplification in patients with cervical squamous cell carcinoma." (PMID 21730982, 2011). "Out of 59 cervical squamous cell carcinomas, 6 (10.2%) showed significant amplification of EGFR." (PMID 21730982, 2011). "The fact that 50 out of 59 (84%) cervical squamous cell carcinomas analysed in this study received radiotherapy may reflect EGFR amplification related to radiation sensitivity." (PMID 21730982, 2011). "In cervical squamous cell carcinoma, CD109 expression enhanced EGFR-induced phosphorylation of STAT3, resulting in increased tumor aggressiveness and stemness activity." (PMID 33375719, 2020).
cervical squamous cell carcinoma (continued). "Moreover, CD109 is responsible for the induction of EGFR-mediated STAT3 regulation in cancer tumorigenicity and aggressiveness, which might reveal a potential molecular target for the development of an effective therapeutic strategy against cervical squamous cell carcinoma." (PMID 32507856, 2020).
corticotroph adenomas (20 papers, 2016 to 2025). "In this systematic review we extracted the information regarding the USP8 variant and the EGFR system in corticotroph adenomas." (PMID 38862897, 2024). "Further, in corticotropinomas, EGFR overexpression is a consequence of 14-3-3 USP8 mutations, which are, in fact, quite specific to this tumor subtype." (PMID 34295309, 2021). "EGFR overexpression in corticotroph adenomas is associated with downstream activation of the ERK pathway." (PMID 32012988, 2020). "The function of EGFR in the adenomaigenesis of CD has been highlighted by the finding of ubiquitin specific peptidase 8 (USP8) mutations in 35–62% of corticotroph adenomas." (PMID 31798535, 2019). "Previous studies have demonstrated that the USP8 mutation causes corticotroph adenomas mainly through activating the EGFR–MAPK signal cascades." (PMID 30093687, 2018). "Based on the previous research of high-frequency mutations USP8 in corticotropinoma, this study tended to explore the regulation of the EGFR pathway by HSP90 involved in the pathogenesis of the tumor, discover potential treatment for Cushing’s disease, and provide evidence for precise treatment." (PMID 33537004, 2020). "Inhibition of expression of USP8 or EGFR could be a potential therapeutic target for patients with corticotropinomas carrying the USP8 mutation." (PMID 33537004, 2020). "Association between EGFR and the clinical characteristics of pituitary corticotroph adenomas." (PMID 31798535, 2019). "Recently, the deubiquitinase gene USP8 was found to be mutated in 35–62% of corticotroph adenomas, resulting in sustained activation of the epidermal growth receptor (EGFR), the mitogen-activated protein kinase (MAPK) pathway, and subsequent overproduction of ACTH7,8." (PMID 30093687, 2018). "EGFR and its pathway signaling molecules had a higher expression in pituitary corticotroph adenomas than in normal pituitary glands." (PMID 37446128, 2023). "EGFR is frequently overexpressed in ACTHomas and is essential for the synthesis of proopiomelanocortin (POMC), an ACTH precursor." (PMID 35954322, 2022). "Among pituitary adenomas, EGFR has been reasonably well studied in corticotropinomas, where IHC positivity in nearly 55% of tumors has been documented." (PMID 34295309, 2021). "Gain-of-function mutations in USP8 have been implicated in aberrant EGFR signaling in corticotrophs and studies show USP8 mutations in 21-62% of corticotroph adenomas." (PMID 34867776, 2021). "EGFR is expressed in 75% of human corticotroph adenomas, and gefitinib treatment of human primary pituitary corticotroph tumor cultures reduced POMC mRNA and reversed features of hypercortisolemia." (PMID 34867776, 2021). "Increased EGFR expression in corticotroph adenomas has been attributed to recently identified somatic mutations in ubiquitin-specific peptidase 8 (USP8), a deubiquitinase enzyme that protects EGFR from degradation." (PMID 32012988, 2020). "Nevertheless, these findings raise the possibility of EGFR-directed therapy, particularly in corticotroph adenomas." (PMID 32012988, 2020). "The epidermal growth factor receptor (EGFR) tyrosine kinase, which is frequently overexpressed in ACTHomas, is one of the deubiquitination substrates of USP8." (PMID 33266265, 2020). "In our study, EGFR and its pathway signaling molecules had a higher expression in pituitary corticotroph adenomas than in normal pituitary glands." (PMID 31798535, 2019). "In the present study, EGFR was overexpressed in 55.8% of the pituitary corticotroph adenomas and in 1 of 6 normal adenohypophysial tissues." (PMID 31798535, 2019). "Epidermal growth factor receptor (EGFR) is expressed to varying degrees in human pituitary tissue, including corticotroph adenomas, and EGFR regulates POMC transcription and ACTH production." (PMID 30147673, 2018).
corticotroph adenomas (continued). "For example, two recently published studies on this subject in humans both show mostly cytoplasmic and membraneous localization of EGFR in corticotroph adenomas despite analysing a large number of tumours." (PMID 28005997, 2016). "Recently, extremely elegant whole-exome sequencing and functional studies have shown that somatic mutations involving theUSP8 gene are found in 35% to 62% of sporadic corticotroph adenomas, providing significant insight into the mechanisms of disease and a direct link with EGFR signaling." (PMID 28529722, 2017). "Moreover, corticotroph-specific EGFR overexpression leads to ACTHomas mediated via E2F1 activation." (PMID 33266265, 2020). "Apart from HIFs, USP8 is involved in epidermal growth factor receptor (EGFR) turnover, thus rescuing EGFR from lysosomal degradation, and mutations in the USP8 gene have been found in corticotroph adenomas, which could cause Cushing’s disease via activation of EGFR signaling." (PMID 31208103, 2019). "Furthermore, we studied the role of USP8 and EGFR protein expression independent of USP8 mutation status in corticotroph adenomas." (PMID 28005997, 2016). "Inhibition of EGFR signaling contributes to the inhibition of ACTH production and cell proliferation in corticotroph adenomas." (PMID 38862897, 2024). "The epidermal growth factor receptor (EGFR) has attracted interest as a potential therapeutic target for resistant and aggressive PA, mainly prolactinomas and corticotroph adenoma." (PMID 33023145, 2020). "Notably, CABLES1 is regulated by Akt, which is part of the EGFR signaling pathway, linking EGF and cell cycle regulation and potentially giving CABLES1 a pivotal role in the pathophysiology of corticotrope adenomas." (PMID 35743266, 2022). "Epidermal growth factor receptor (EGFR) is expressed to varying degrees in human anterior pituitary glands, non-functional and functional pituitary adenomas, including corticotroph adenomas." (PMID 31798535, 2019). "Although EGFR is expressed in other lineages of aggressive pituitary tumors, our findings suggest that EGFR signaling induces E2F1-mediated POMC transcription and corticotroph adenoma pathogenesis." (PMID 30147673, 2018). "The expression of EGFR was strong in corticotroph adenomas but not in normal pituitary glands." (PMID 31798535, 2019). "Moreover, densitometric analysis revealed that the EGFR levels in the recurrent corticotroph adenomas were significantly increased compared to those in the non-recurrent corticotroph adenomas." (PMID 31798535, 2019). "Moreover, Pasireotide as well as inhibitors of EGFR such as Gefitinib and Lapatinib, as well as USP8 inhibitors including -ehtyloxyimino9H-indeno (1, 2-b) pyrazine-2, 3-dicarbonitrile, DUBs-IN-2, and RA-9 indicated promising results in treatment of corticotroph adenomas." (PMID 38862897, 2024).